EPCAM (epithelial cell adhesion molecule)
Diseases named in the same sentence as EPCAM in open-access papers (continued):
Sharing a sentence is not in itself a finding about the gene and the disease.
tumor (continued). "Gene set enrichment analysis (GSEA) pathway analysis revealed that the complement system, WNT signaling, DNA replication, VEGFA-VEGFR2 signaling, and metabolic reprogramming were the top five ranked pathways in EPCAM(+) tumor epithelial cells of EOCC." (PMID 37964075, 2023). "Although we still lack an exclusive tumor-cell-derived BC marker for EVs, some tumor markers, such as CD49f or the epithelial cell-specific marker (EpCAM), have shown promising results in this regard." (PMID 37629204, 2023). "(A–C) Immunofluorescent four-colour staining of oral tumour specimens for EpCAM (yellow), Vimentin (red) and CD24 (green) with DAPI nuclear stain (blue)." (PMID 37975646, 2023). "The device was functionalized with anti-EpCAM antibodies, enabling the capture of circulating tumor cells (CTCs) from peripheral blood samples." (PMID 37754116, 2023). "In vivo, non-tumor tissue showed the emergence of epithelial cells expressing the stem cell marker epithelial cell adhesion molecule (EpCAM), which increased in number under the conditions of sustained inflammation in PtenΔhep mice." (PMID 37896221, 2023). "The assay discriminates tumor cells from “normal” cells by selectively recognizing the expression of the epithelial cell adhesion molecule (EpCAM)." (PMID 36835424, 2023). "RHOJ overexpression in EPCAM+ tumour cells strongly decreased the proportion of apoptotic tumour cells 24 h after cisplatin/5FU administration and leads to increased cell survival 48 h after chemotherapy." (PMID 36949199, 2023). "BM aspirates from 104 non-metastasized NSCLC patients that underwent potentially curative tumor resection revealed CK+ and EpCAM+ DTCs in half of the patients, respectively." (PMID 37303738, 2023). "In vivo, relative to that of the Dox alone treatment group, EpCAM-apt-Dox induced more than 40% reduction in tumor weight and size." (PMID 36969696, 2023). "In parallel, we utilized multiplex-immunofluorescence (IF) to map the intra-tumoral localization of CAR T cells (GFP+ cells) in vivo and to determine their spatial relationships with their respective FAP+ stromal cell and EpCAM+ tumor cell targets." (PMID 37607999, 2023). "Epithelial cell adhesion molecule (EpCAM), a homophilic transmembrane adhesion protein, is a highly studied tumor antigen." (PMID 37192201, 2023). "We analyzed the relationship of BAP31 with 84 kinds of tumor-associated antigens and found that BAP31 is positively correlated with the protein level of EpCAM." (PMID 37834237, 2023). "It uses an EpCAM antibody capture system and cytokeratin antibodies for identifying tumor epithelial cells." (PMID 38065965, 2023). "EpCAM-positive circulating tumor cells (CTC) have a high predictive value for early HCC recurrence after curatively intended resection, most likely indicating micro-metastases at the time of resection." (PMID 38012205, 2023). "The cell cycle profile of EPCAM+ and EPCAM− cells was comparable in the untreated condition, whereas Rhoj-KO EPCAM− tumour cells presented an increase in G0/G1 at the expense of S phase." (PMID 36949199, 2023). "Previously, however, we achieved high peak tumor signal with the epithelial cell adhesion molecule (EpCAM) targeting Fab VB6-845-IRDye800CW resulting in clinical translation (NTR7570)." (PMID 34642899, 2023). "Proof-of-concept studies were performed in 2008 when tumor-derived exosomes were enriched by a modified magnetic activated cell sorting procedure, using anti-epithelial cell adhesion molecule (EpCAM)." (PMID 37109414, 2023). "Blocking the tumor cell surface antigen EpCAM is a novel strategy for inhibiting tumor cell growth and metastasis and improving treatment efficacy in TNBC." (PMID 37457288, 2023). "Restricting the analysis to EPCAM+Lin− tumor epithelial cells, we identified the enriched gene sets in each BC molecular subtype." (PMID 37190091, 2023).
tumor (continued). "EpCAM is a druggable target with many on-going clinical trials and thus, patients with tumours expressing this marker are likely to benefit from this therapy in the future." (PMID 37533952, 2023). "EpCAM staining was always intense in normal urothelial cells (14.2 ± 14.5) and - among tumors - it was highest in pTa G2 low grade neoplasms." (PMID 38282671, 2023). "Carboplatin-treated PDX-287R grafts had a significant decrease in the proportion of EpCAM+ tumor epithelial cells 1 week following treatment compared to vehicle-treated grafts." (PMID 37660083, 2023). "ICAM-1 can induce the secretion of proinflammatory cytokines upon CAR interaction with the primary antigen EpCAM; thus, tumor cells are more vulnerable to dual CAR T cells." (PMID 36707873, 2023). "According to clinicaltrials.gov, current clinical trials involve a study done in University Hospital Zurich, Switzerland for the use of magnetic NPs, coated with epithelial cell adhesion molecule (EpCAM)–antibodies to target epithelial tumor cells." (PMID 38053150, 2023). "We also observed a lower H4 signature in the solid primary tumor YFP + EpCAM, indicating partial EMT, whereas the solid YFP + metastatic organoids had a higher mesenchymal signature, suggesting that the metastatic organoids progressed towards complete EMT." (PMID 36828915, 2023). "While each PDX sample was transduced equivalently at t = 0, the relative frequency and total number of GFP + EpCAM+ tumor cells were reduced by 2–50-fold in shSmarcd3 tumors at endpoint." (PMID 36653361, 2023). "Further analysis of the CCL5/Sp1/CD44 axis in EpCAM+ cells revealed that this signaling pathway was more activated in advanced tumor stages, which was consistent with the protein analysis." (PMID 37553567, 2023). "The YFP reporter, combined with EPCAM staining, enables us to identify tumour cells that undergo EMT and lose the expression of epithelial markers (YFP+EPCAM−)." (PMID 36949199, 2023). "These differential expression patterns have positioned EpCAM as an interesting antigen for targeted cancer therapy although EpCAM-targeted therapies must be closely assessed for on-target/off-tumor binding potentially resulting in adverse effects." (PMID 36845124, 2023). "Clinically, circulating-tumor cells (CTCs), which express EpCAM, MET, and CD44, identify a subset with increased metastasis-initiating phenotype, suggesting that CD44v6 plays an important role in cancer-initiating cell property cooperating with MET." (PMID 36835416, 2023). "The most common CD133 aptamer used for research has the sequence: 5′-CCCUCCUACAUAGGG-3′, and EpCAM aptamer with the sequences 5′-ACGUAUCCCUUUUCGCGU-3′ or 5′-GCGACUGGUUACCCGGUCG-3′ is frequently used as a targeting ligand for CSCs in different tumor types." (PMID 36969696, 2023). "The gene expression profiles in EPCAM(+) tumor epithelial cells were compared between EOCC and LOCC samples to determine distinctive pathways." (PMID 37964075, 2023). "CRC in this study preferentially overexpress EpCAM over E-cadherin whose strong cell-cell contact inhibitory role is weakened even when expressed, resulting in further local tumour spread." (PMID 37533952, 2023). "The immunoaffinity enrichment method for exosome isolation allows good differentiation between cancer cell-originated exosomes and normal cell-originated exosomes using antibodies and inducers targeting tumor-associated proteins such as CD81, GPC-1, and EpCAM." (PMID 36627698, 2023). "tracked TEXs through the tumor biomarker EpCAM and then recognized TEXs through the aptamers for EpCAM and PD-L1." (PMID 37736550, 2023). "In turn, the suppression of cell cycle in malignant cells upon anti-PD1 treatment resulted in a reduction of epithelial (EPCAM+) cells in the tumors, supporting the tumor size shrinkage observed on the anti-PD1 treated mice." (PMID 36973261, 2023).
tumor (continued). "EpCAM is frequently expressed on tumor cells of epithelial origin, while its expression and accessibility in normal epithelial tissue are limited." (PMID 37485031, 2023). "Tumor epithelial cells were enriched in EpCAM and keratins, as well as markers of the fallopian tube epithelium." (PMID 38248751, 2023). "The primary tumor surface marker that is currently commercially available for CTC detection is the epithelial cell marker EpCAM." (PMID 37569448, 2023). "The epithelial cell adhesion molecule (EpCAM) that is expressed in many human carcinomas and cancer stem cells is another promising tumor target." (PMID 36977072, 2023). "Both constructs effectively degraded Ras proteins in EpCAM-positive cells in both 2D and 3D tumor-on-a-chip systems." (PMID 37485031, 2023). "EPCAM− tumour cells were very resistant to chemotherapy-induced cell death in vivo as only 2% of EPCAM− tumour cells were caspase-3 positive compared with 9% of epithelial EPCAM+ tumour cells." (PMID 36949199, 2023). "These properties would project EpCAM as a poor prognostic tumour marker, but its role as a weak cell aggregator among fibroblasts would suggest a favourable prognosis under differing conditions." (PMID 37533952, 2023). "The results showed higher expression levels of both genes in CD44+c-Myc+EpCAM+ cells, indicating that CSCs were more resistant to gemcitabine with tumor development." (PMID 37553567, 2023). "A CD40 × EpCAM bsAb has been designed to satisfy the need of tumor antigens in the activation of DC83." (PMID 36971124, 2023). "Using a tissue sample of the diaphragm with macroscopic tumor lesions, another possible tumor marker, EpCAM (Epithelial adhesion molecule), was evaluated." (PMID 37077833, 2023). "To summarize, FAP(+) CAFs as well as EPCAM(+) tumor epithelial cells show an upregulation of WNT signaling." (PMID 37964075, 2023). "Its isolation is based on anti-epithelial cell adhesion molecule (EpCAM) antibodies for the positive capture of tumor cells of epithelial origin." (PMID 37363395, 2023). "Both UBS54 and Y6V-iIL-12 CAR-T cells suppressed the progression of SRCC24 tumors which expressed strong EpCAM, in comparison with insignificant tumor killing by NT, Y6V, and iIL-12 T cells." (PMID 37045815, 2023). "We further examined CD70 expression on NPC cells isolated from fresh endoscopic biopsies via flow cytometry, showing that approximately 60% of EPCAM+ tumor cells were CD70+, whereas only 10% CD70+ cells in EPCAM- infiltrating immune/stromal cells." (PMID 37024479, 2023). "High coexpression of CD44, CD90 and vimentin and spindle shaped morphology, in combination with loss of EpCAM and retention of E-cadherin indicates partial EMT (pEMT) typical of aggressive tumor cells." (PMID 37063842, 2023). "The frequency of CD47+ cells positively correlated with the frequency of EpCAM+ tumor cells within both spheroids and tumoroids." (PMID 37876933, 2023). "Despite the role of EpCam as mediator of epithelial cell-cell adhesion, some works mention it as a marker of tumor initiating cells." (PMID 36875773, 2023). "Recognition of EpCAM or B7-H3 on ROR1+ tumor cells activated the synthesis of a transcription factor that, in turn, promoted the transcription of the ROR1 CAR gene." (PMID 36873868, 2023). "Aptamers against CD44, CD133, and EpCAM have been tested as targeting ligands in a variety of tumor types." (PMID 36969696, 2023). "Using cell fractions mode, cell proportions of EPCAM(+) tumor epithelial cells, FAP(+) CAFs, CD45(+) leucocytes, and CD31(+) endothelial cells were generated for each tissue sample." (PMID 37964075, 2023). "Further, tamoxifen-mediated Smarcd3 deletion led to a ~3-fold drop in total free fatty acid content in EpCAM+ Smarcd3f/f-KPF-R26-CreERT2 tumor cells in vivo, as determined by gas chromatography–mass spectrometry (GC–MS)." (PMID 36653361, 2023).
tumor (continued). "When applied in immunotherapy, catumaxomab (CD3 × EpCAM), the first approved bsAb for cancer treatment, bridges tumor cells and T cells, representing a milestone in bsAb therapy." (PMID 36971124, 2023). "Both in vitro and in vivo experiments have demonstrated the vector’s ability to specifically target EpCAM-positive tumor cells." (PMID 38082377, 2023). "To distinguish between these two possibilities, we investigated apoptosis in EPCAM+ and EPCAM− tumour cells 24 h after chemotherapy administration." (PMID 36949199, 2023). "Preclinical investigations in mice employing a cancer xenograft model revealed that intravenous injection of EpCAM-CAR T-cells resulted in considerable tumor control." (PMID 37020537, 2023). "The CD133+/EpCAM+ subgroup of LCSCs shows higher tumor-initiating activity than the CD133+/EpCAM− and CD133−/EpCAM+ subgroups of LCSCs59." (PMID 38009775, 2023). "The use of an orthogonal marker to EpCAM, which we present to be FAP, allows for better disease staging and monitoring of the tumor response to treatment even if EpCAM is downregulated." (PMID 37759489, 2023). "Among the EpCAM-positive tumours, 83.3% (30/36 positive cases) showed marker overexpression (total immunoscore ≥4)." (PMID 37533952, 2023). "The CellSearch (Verdex LLC, San Diego, CA, USA), which is presently the only US Food and Drug Administration (FDA)-approved method for CTCs, is based on the expression of epithelial cell adhesion molecules (EpCAM) on tumor cells." (PMID 37998398, 2023). "Regarding the suggested interplay between the two axes CD47:SIRPα and HLA class I:LILRB1 in counteracting effective ADCP of tumor cells as demonstrated for anti-EpCAM or anti-EGFR antibodies, additional antibody combinations were studied." (PMID 37781391, 2023). "Consistent with the previous set of tumours, only EpCAM+Vim+CD24+ cells were specifically enriched in the stroma of metastatic tumours." (PMID 37975646, 2023). "In reference to the in vivo assays, EpCAM-redirected CAR-Ts significantly reduced tumor burden in preclinical mouse models in comparison with control T cells." (PMID 38146364, 2023). "The results indicated that RAC3 was mainly co‐localized with EPCAM, a considerable marker highly expressed in epithelial tumour cells." (PMID 37386813, 2023). "Recently, the EpCAM AUA1 antibody was used to detect circulating tumor cells, which can be used for the early detection of many carcinomas." (PMID 37345198, 2023). "Our data suggested that EpEX and HGFR coordinately stimulate downstream HGFR signaling to promote tumor progression and cell invasion, so we wanted to further test the anti-tumor effects of simultaneously blocking both EpCAM and HGFR signaling." (PMID 37543570, 2023). "Circulating tumour cells (CTCs) are mainly enriched based on the epithelial cell adhesion molecule (EpCAM)." (PMID 36823365, 2023). "For these tumours, using a variation on the previous image segmentation protocol, the proportion of EpCAM+Vim+CD24+ and EpCAM+Vim+CD24- cells was quantified for each cell in over 9000 imaging fields at the tumour-stroma boundary." (PMID 37975646, 2023). "EpCAM is present in a variety of cancer types and is crucial for tumor metastasis, cell proliferation, and adhesion." (PMID 36990999, 2023). "This antibody has two distinct antigen-targeting sites—one for the CD3 antigen on T-cells and another for the EpCAM on tumor cells—and also binds to accessory cell FcγR via its preserved Fc region." (PMID 38106416, 2023). "By using this system, researchers were able to effectively immobilize circulating tumor cells with the aid of anti-EpCAM antibodies and demonstrated the potential of this system as a plug-and-play device for rapid and easy oral cancer screening." (PMID 39916924, 2023). "EpCAM, a transmembrane glycoprotein that is highly expressed in various types of cancer and has been identified as a tumor marker of epithelial origins for nearly four decades, was used to identify tumor cells in this study." (PMID 37553567, 2023).
tumor (continued). "Epithelial cell adhesion molecule (EpCAM) represents a well-known molecule whose expression has been related to poor prognosis and tumor metastatization." (PMID 36900394, 2023). "A large group of human RMC tumour cells were identified with high expression of EPCAM and the bulk RMC signature as well as a group of murine cells corresponding to CAFs and pericytes, TAMs and monocytes, and a smaller number of other immune cells." (PMID 37236926, 2023). "The TROP2/EpCAM ratio was also unrelated to overall and tumor specific survival in pT2-4 carcinomas." (PMID 38282671, 2023). "We stained and imaged 59 tumour slides from 54 regions across 50 tumours, stratified on the same criteria as the previous cohort, for EpCAM, Vimentin and CD24." (PMID 37975646, 2023). "Despite advanced tumor stage at enrollment, Smarcd3 deletion reduced total tumor cell and EpCAM+ tumor cell number by 1.5 fold." (PMID 36653361, 2023). "EpCAM has an increased level of expression on epithelial tumor cells, such as adenocarcinomas of the colon, stomach, pancreas, and prostate." (PMID 36769161, 2023). "These Grem1-positive EMT-tumor cells reduced Snail and Slug expression in neighbouring EpCAM + cells, thereby maintaining their epithelial state (“Good GREM1”)." (PMID 37615860, 2023). "Epithelial cell adhesion molecule (EpCAM)—a homophilic cell–cell adhesion glycoprotein—is a well-known tumor antigen expressed on epithelial tumors, circulating tumor cells, and cancer stem cells." (PMID 36918661, 2023). "Similar to tumors derived from bulk PROCR+/EpCAM− transformed cells, tumors derived from the single cell derived clone were also PROCR+ and spindle shaped with pockets of EpCAM+ tumor cells." (PMID 37709737, 2023). "In patients with SD compared to those with PD, we found markers including CD163, EpCAM, PR, and B7-H3, enriched in the tumor compartment of patients with SD." (PMID 37153589, 2023). "The identification of CSC surface markers such as EpCAM, CD44, and CD133 has caused the identification of specific therapeutic targets for inhibiting tumor recurrence and metastasis." (PMID 36810098, 2023). "An increased response to anti-PD-1/anti-PD-L1 ICB alone correlated with a high frequency of CD3+ T cells and PD-L1+/EPCAM+ tumor cells and was seen in a small number of patients." (PMID 37627156, 2023). "By utilizing epithelial cell adhesion molecule (EPCAM) staining to identify tumor cells undergoing EMT, it was observed that the tumors resistant to chemotherapy were highly enriched with EPCAM− cells." (PMID 37779170, 2023). "There also appear to be regions of PD-L1 positivity on the EpCAM tumor cells that are accessible to target with ICB immunotherapies." (PMID 37627156, 2023). "Unique to the CTC assay was the co-isolation of epithelial CTCs (EpCAM) and mesenchymal CTCs (FAPα), which better recapitulated the complex tumor microenvironment compared with using epithelial CTCs only." (PMID 37759489, 2023). "Altogether, these observations lead to the conclusion that EpCAM dependently and independently enriched CTCs originate from identical tumour cell clones that most likely represent a tumour surrogate material of similar relevance." (PMID 36823365, 2023). "Chimeric antigen receptor-modified T cells (CAR-T) have the ability to target tumor antigens such as EpCAM, and can specifically recognize, bind to, and kill antigen-positive tumor cells." (PMID 36899854, 2023). "This, therefore, suggests an inherent effect of tumour biology on EpCAM expression devoid of influence from age, gender or tumour location as alluded to above." (PMID 37533952, 2023). "To identify novel therapeutic targets for each BC molecular subtype, we conducted differential expression analysis focusing only on tumor epithelial cells (EPCAM+Lin−) and identified the gene set(s) most enriched in each BC molecular subtype." (PMID 37190091, 2023).